CCR7 (C-C motif chemokine receptor 7)
Diseases named in the same sentence as CCR7 in open-access papers (continued):
Sharing a sentence is not in itself a finding about the gene and the disease.
tumor (continued). "C–C Motif Chemokine Ligand 19 (CCL19) is a chemokine, and its upregulation inhibits GC cell proliferation and tumor growth by upregulating the C–C Motif Chemokine Receptor 7 (CCR7)/AIM2 axis, while silencing AIM2 abrogates the effects of CCL19 on tumor growth." (PMID 41291696, 2025). "As a central memory subset expressing CCR7 and CD62L has been shown to be more effective at controlling tumor in vivo than an effector memory subset, we assume this is a clear benefit of using Ko-Op for γδ T cell expansion." (PMID 41369406, 2025). "Overall, the flow cytometry analysis validated the scRNAseq data and showed that activated cDC1s and cDC2s within tumours can exist in two states, differentially expressing CXCL9 or CCR7." (PMID 40745918, 2025). "Research indicates that tumor tissues expressed ligands for these receptors of chemokines, with the interactions of CXCL12‐CXCR4, CXCL10‐CXCR3, and CCL19 –CCR7 play crucial role in attracting CD8+ T cells to infiltrate tumors." (PMID 39727149, 2025). "Spatial distribution analysis using the STOmics DB database also showed that SUSD3 co-localized with the tumor cell marker ANXA1 and the T cell marker CCR7 in SKCM cancer tissues, indicating spatially similar distributions." (PMID 40191190, 2025). "In vivo validation confirmed that pharmacological CCR7 or STAT3 inhibition markedly reversed chemoresistance and potentiated cisplatin-induced tumor cell death." (PMID 40898244, 2025). "In vivo experiments reinforced the efficacy of lenalidomide, significantly reducing tumor growth rate, tumor mass, serum total LDH levels, and expression of CCR7 and p-ERK1/2 in a SU-DHL-2 xenograft model in nude mice (p < 0.05)." (PMID 39735670, 2025). "Intratumoral migratory CD103+ cDC1s are the major type of APCs that transport tumor antigens to the tumor-draining lymph nodes (TdLNs) to elicit a specific CD8+ T-cell response, and this process is CCR7 dependent." (PMID 41291775, 2025). "CCR7 interacts with its ligand CCL21, which is found at higher levels in the extracellular matrix of tumor lesions." (PMID 40861461, 2025). "The experimental results revealed the presence of CCR7+ cells within lymphatic vessels induced by VEGF-C, which indicated that CCR7+ cells migrated into the tumor through the lymphatic vessels." (PMID 40685403, 2025). "Positive staining of CCR7 protein was primarily observed on the membrane and in the cytoplasm of tumor cells, and based on the staining score of tumor tissue, HCC patients were divided into CCR7-high expression group and CCR7-low expression group." (PMID 40685403, 2025). "Finally, whether the retention of CCR7+ DCs in tumours is due to the acquisition of aberrant trafficking behaviour or due to intratumoral interactions, such as chemoattraction to stromal cells or tumour cells expressing CCR7 ligands remains to be resolved." (PMID 38267413, 2024). "Six tumor-infiltrating CD4+ T-cell clusters (CD4+_FOXP3, CD4+_CCR7, CD4+_LMNA, CD4+_ISG15, CD4+_CXCL13 and CD4+_MKI67) were identified after data filtering, integration, unsupervised clustering and annotation." (PMID 38383773, 2024). "Monocyte scores showed a significant positive correlation with the expression of TM cell marker genes including SELL, CCR7, and IL7R in most tumor types." (PMID 38386350, 2024). "Most studies investigating the key regulatory role of chemokine receptors in tumor progression and spread focus on the CXCR4-CXCL12/CCR7 axis." (PMID 39001456, 2024). "CCR7 expression, involved in lymphocyte migration to lymph nodes, remains unchanged, while CXCR3, mediating NK cell recruitment to tumor sites, is enhanced in expanded NK cells." (PMID 38474415, 2024). "We have also demonstrated infiltration of CD45, Macrophages, and NK cells into the tumor stroma, and upregulation of KLRG1, Sell, Ccr7, and IL7r upon the treatment with ICG-001 and then CAR Ts." (PMID 38449858, 2024).
tumor (continued). "Molecules involved in CCR7+ DC-CD8+ T cell crosstalk were expressed in these voxels, with spatial correlation of CCR7+ DC-CD8+ T cell ligand-receptor pairs in all 3 tumour types." (PMID 38267413, 2024). "We identified a CCR7+ DC-CD8+ T cell axis, including specific interactions which control anti-tumour cytolytic activity." (PMID 38267413, 2024). "However, the spatio-temporal dynamics of CCR7+ DCs in anti-tumour immune responses remain unclear." (PMID 38267413, 2024). "Studies have shown that CCR7, known for mediating T cell entry into secondary lymphoid organs, is crucial in forming CD103+CD8+ T cells and its tumor-clearing capabilities." (PMID 39391310, 2024). "Another approach to recruiting T cells into tumor is to use constructs expressing a chemokine receptor, such as CCR2, CCR2b, CXCR3, CCR4, CCR7, CXCR2, or CXCR4, which can interact with the relevant tumor-derived chemokine." (PMID 38927974, 2024). "The tumor-infiltrating cDC1 and cDC2 displayed a migratory and activated phenotype shown by CD40 and CCR7 expression, the RNA-seq data revealed overall upregulation of Cd40, Cd86 but also the cytokine Il12 in BRAFi-sensitive tumors." (PMID 38631706, 2024). "Patients with high CCR5, CCR7, CXCR4, and CXCR5 expression on tumors and high CXCR4 expression on tumor-infiltrating lymphocytes were less likely to have a chemotherapy response compared to others." (PMID 39001456, 2024). "In vitro studies have shown that C-C motif chemokine receptor 7 (CCR7) expression on DC cells co-cultured with type I IFN promotes DC homing migration and migration to tumor-draining lymph nodes." (PMID 39834588, 2024). "To investigate which stromal cells are affected by CCR7 in OSCC, we performed scRNA-seq analysis in WT and KO tumor tissues." (PMID 38539232, 2024). "Conversely, also in lung cancer, CCR7/CCL19 can promote the upregulation of heparanase-1 in the TME, contributing to the migration and invasion of A549 tumor cells, and lymph node metastasis." (PMID 38786066, 2024). "CCR7 with its ligands CCL21 and CCL19 regulates the apoptosis of CD8 + T cells and participates in the process of tumor microenvironment remodeling." (PMID 37864213, 2023). "Studies have shown that EV-packaged CCR7-induced tumor cells recognizes and accumulates toward lymphogenic CCL19 and CCL21, thereby promoting preferential tumor cell localization in sentinel LNs1." (PMID 36971125, 2023). "It was also shown that the majority of infiltrating CTLs in tumor beds exhibited effector (CD8+CD28+), memory (CD45RO+), or activated phenotype (CD25+, CD69+, HLA-DR+) and the naive subset (expressing CD45RA and CCR7) compromised the least proportion." (PMID 37835465, 2023). "ThyroidPrint® is a novel q-PCR-based ten-gene classifier with its signature representing both the tumor microenvironment (CXCR3, CXCL10, CCR3, CCR7, and CXADR) and tumor epithelial cells (TIMP1, CLDN1, KTR19, AFAPL2, and HMOX1)." (PMID 37671897, 2023). "While there were substantially fewer CD45RA+CCR7− CD8+ effector-like CAR-T cells in the A0.15 product relative to A0.1 product, both led to similar degrees of tumor control." (PMID 36720856, 2023). "Accordingly, tumor-derived VEGF-C has been observed to induce CXCL21 secretion by LVs, thus mediating CCR7-dependent lymphatic invasion of cancer cells." (PMID 38068914, 2023). "Within the CD8 tumor-infiltrating T cells cluster, SNX9 expression was negatively correlated with the expression of central-memory and progenitor markers, CCR7 and TCF7." (PMID 36732507, 2023). "In cancer CCR7 is upregulated together with CXCR4, and the dimer formed by both can activate signaling pathways and promote tumor metastasis." (PMID 37864213, 2023). "We also found that patients with larger tumor size (> 4 cm) had significantly higher expression of MMP-9 and CCR7 (P<0.002 and P<0.001, respectively)." (PMID 37600570, 2023).
tumor (continued). "In our screen, we found two chemokine receptors to very specifically direct T cells into tumor-draining lymph nodes: CCR4 and CCR7." (PMID 37301772, 2023). "As expected, most of the CAR-T cells on the tumor site showed higher levels of the immunoinhibitory molecule PD1 and reduced expression of the memory marker CCR7 compared with the in vitro cultured T cells." (PMID 36906640, 2023). "In conclusion, we constructed the first prognostic model based on the CCR7/CCL19 chemokine axis in BC and explored its role in immune infiltration, tumor microenvironment, and HLA genes." (PMID 37864213, 2023). "We constructed the first prognostic model based on the CCR7/CCL19 chemokine axis in BC and explored its role in immune infiltration, tumor microenvironment, and HLA genes." (PMID 37864213, 2023). "Up-regulating the expression of CCL19 in tumors can inhibit its growth by effectively recruiting CCR7 + DC and IFN-γ + CD8 + T cells into tumor locations, which can be a powerful anti-tumor treatment combined with anti-PDL150." (PMID 38049474, 2023). "To further characterize MDSC-DCs obtained from different origins and culture systems, we examined expression levels of several DC markers, such as CD24, CCR7, CD117, and CD135 on the MDSC-DCs in 4T1-tumor bearing mice." (PMID 35707772, 2022). "The expression of the C-C chemokine receptor 7 (CCR7), the chemokine receptor for CCL19/CCL21, by DCs is important to facilitate their trafficking between the lymph nodes and the tumor." (PMID 35267487, 2022). "It has been reported that the interaction between CCR7 and MAPK plays a vital role in the cell migration and lymphatic metastasis of several tumours." (PMID 35280672, 2022). "Flow cytometric analyses of tumor suspensions exhibited greater tumor infiltration of CD8+ DCs, CCR7+ DCs, and NK cells in the combination group, as well as reduced levels of myeloid-derived suppressor cells (MDSCs) in vaccinated groups." (PMID 36741387, 2022). "We found that only five genes (MITF, CCR7, JAK1, ELN, and SLC6A4) functioned as tumor suppressors, whereas the remaining 17 genes functioned as oncogenes." (PMID 36425071, 2022). "In parallel, glucomannan can also inhibit the expression of major chemokine receptors, chemokine receptor 4 (CXCR4) and CC chemokine receptor 7 (CCR7), found in a wide range of tumor cells, thus reducing the dissemination ability of tumor cells." (PMID 36360194, 2022). "Specimens from 41 patients with T-cell non-HL having lymphoid hyperplasia were investigated and showed elevated levels of CCR7 and MMP-9 correlating with increased numbers of cancerous lesions and higher tumor stage." (PMID 35203305, 2022). "The blockade of JNK and p38, a downstream signal of CCL21/CCR7, in PTX-treated tumour cells resulted in a decreased migration of tumour cells." (PMID 35280672, 2022). "Other tumor angiogenesis-related chemokines and their receptors, such as CCL21/CCR7 and CXCL4, can be used as targets for anti-tumor angiogenesis therapy." (PMID 35770088, 2022). "A significant negative correlation was found between the expression level of CCR7 and CCL19 and miR let-7a in tumor tissue (p = 0.0007, rho = −0.426 and p = 0.00002, rho = −0.521, respectively, Spearman’s rank correlation)." (PMID 35160116, 2022). "Although tumor-infiltrating mregDCs express key cDC1s and cDC2s markers (e.g., XCR1L, CD103 or CD11b), they are distinguished from them by higher CCR7 expression." (PMID 36230990, 2022). "And the expression of HAVCR2, CCR7 and CD28 had poor correlation with the clinicopathological features of PCa in age, GS and tumor stage." (PMID 36505767, 2022). "Tumor-infiltrating pDCs are also able to recruit other suppressive cells in the tumor microenvironment such as myeloid suppressive cells, IL10+CCR7+CD8+Foxp3+ induced Tregs, and IL-10+ IL-17+ Foxp3neg type-1 regulatory T cells (Tr1)." (PMID 35884612, 2022).
tumor (continued). "This research is a continuation and extension of our earlier study, the aim of which was to evaluate changes in the expression level of CCR7 and CCL19 in tumor tissue and of two regulatory miRNAs of these genes (miR let-7a and miR-335) in serum exosomes." (PMID 35160116, 2022). "Recently CCL19/CCR7 axis has been identified to modulate EMT and mediate tumor cell invasion and migration through the AKT signaling pathway in BC48." (PMID 35725915, 2022). "Cluster 1 is composed of naive CD8+ T cells and is characterized by expression of CCR7 and CD45RA; its exclusion from tumor samples is indicative of minimal blood contamination of BrM specimens." (PMID 35584630, 2022). "In contrast to the controls, the protein expressions of CXCR4, CXCL12, CCR7, CCL21, P-ERK1/2, MMP-9, and MMP-2 in SK-Hep1 cells were significantly increased after transfection of tumor-derived DNA, while the increase was reversed by sinobine hydrochloride." (PMID 35860597, 2022). "DC migration to and between the tumour and lymphatic system is controlled by a range of chemokine receptors, including CCR5, CCR6, and CCR7." (PMID 35205725, 2022). "When all HPV16-positive mothers were pooled together, they had also higher levels of terminally differentiated (TEMRA) CD8+ cells (CD45RA+CCR7−), which are the most effective CD8+ cells in destroying tumor cells and virus-infected cells." (PMID 36560637, 2022). "For example, CCR7 and its ligands (CCL19/CCL21) are a vital axis for carcinogenic properties, such as epithelial-mesenchymal transition, tumor invasion and migration." (PMID 36291815, 2022). "The clinical course of BPDCN shows progressive systemic expansion, partially attributed to the local production of chemokine ligands of CKR expressed by the tumor cells (CXCR3, CXCR4, CCR6, CCR7)." (PMID 34778050, 2021). "A seminal report showed CCR7 to be a functional receptor that is highly expressed in 4 of 5 T-ALL cell lines and in PB tumor cells of 8 of 11 T-ALL patients." (PMID 34778050, 2021). "In clinical practice, CCR7 is sporadically detected by flow cytometry in AML samples from PB and BM in a small proportion of tumor cells (unpublished data)." (PMID 34778050, 2021). "However, CCR7 could also be expressed by the tumor cells themselves." (PMID 34122408, 2021). "Activated DCs contribute to anti-tumor immunity by increased expression of MHC class II, costimulatory molecules and C-C chemokine receptor type 7 (CCR7), and high ability to produce cytokines." (PMID 34571910, 2021). "DC2s displayed decreased monocyte lineage markers and increased expression of cDC receptors, including CCR7 and Clec9a, leading to increased DC2 migration out of the tumor microenvironment." (PMID 34283809, 2021). "Moreover, naïve tumor-specific CD8+ T-cells, which seem less susceptible to anti-CCR7 therapy, can also become activated and gain effector-cell phenotypes directly at the tumor site, suggesting that cross-presenting DC are also able to prime CD8+ T-cells within the tumor." (PMID 34778050, 2021). "Recently tenascin-C was shown to contribute to the immune-suppressive microenvironment of the tumor stroma through integrin α9β1 inducing CCL21 (in lymphatic endothelial cells) and TLR4 regulating CCR7 (in CD11c+/dendritic cells)." (PMID 33912190, 2021). "This in turn minimizes harmful effects of CCR7, including undesirable activation of Akt‐GSK3 pathway in tumor cells." (PMID 33934539, 2021). "FL tumor cells expressing CXCR4, CXCR5 and CCR7 home in both BM and LN, and the interaction of CXCR12 expressed on BM stromal cells of the lymph node/BM with CXCR4 expressed by tumor cells, has been found to play a critical role in this context." (PMID 34395425, 2021). "During tumor metastasis through the initial lymphatics, lymphatic endothelial cells were known to secrete CCL21 and attracted cancer cells expressing CCR7 and CCL21 receptors." (PMID 34671596, 2021).
tumor (continued). "The low levels of CCR7 on CD4+ and CD8+ T cells in the tumor tissue compared to the blood of tumor patients are shown in representative density plots." (PMID 32082401, 2020). "CCL21, through binding to its receptor, chemokine (C-C motif) receptor 7 (CCR7), can attract dendritic cells (DCs), lymphocytes, natural killer (NK), and natural killer T (NKT) anti-tumor effectors to the tumor site." (PMID 29687228, 2020). "Triple-NR4A-knockout CAR T cells decrease the expression levels of CCR7, PD-1, and TIM3, which induces tumor regression and prolonged the survival of tumor-bearing mice." (PMID 32423475, 2020). "Chemokine axes such as CCL19, CCL21/CCR7, CCL20/CCR6, CXCL12/CXCR4, and CXCL13/CXCR5 correlate with B cell infiltration to tumor sites." (PMID 31991604, 2020). "Studies have shown that C-C chemokine receptor type 7 (CCR7), a G protein-coupled receptor, is the receptor of CCL21 and aberrantly expressed in certain tumor types." (PMID 33158173, 2020). "Meanwhile, expression of the three chemokines were correlated to histological type, tumor differentiation, LVI and survival; expression of CXCR4 and CCR7 were also correlated to recurrence; and CCR7 expression differed notably between sexes." (PMID 32896997, 2020). "Expression levels of CXCR4, CXCR5 and CCR7 were significantly higher in tumor tissues, and expression of CXCR5 and CCR7 were independent prognostic factors for survival." (PMID 32896997, 2020). "CCR7 expression levels in human tumors correlated positively with signatures of CD141+ DCs and intra-tumor T cells, as well as better clinical outcomes." (PMID 32746880, 2020). "Consistently, the tumor volumes were significantly larger in the anti-CCL21 and anti-CCR7 treatment groups than in the IgG control group." (PMID 32094452, 2020). "Recently, CCR7-expressing CD103+ DCs were identified as trafficking between tumor site and tdLN, transporting tumor antigen, and priming a T cell anti-tumor response." (PMID 33268774, 2020). "With increasing age, expression of immunosuppressive CD73 and CCR7 was lower and expression of PD1 elevated on peripheral T cells in healthy volunteers and tumor patients." (PMID 32082401, 2020). "Oxysterols that can activate LXRα signalling in DCs inhibit expression of C-C motif chemokine receptor-7 (CCR7) on the DC surface, thus consequently suppressing the presentation of tumour antigens to T cells." (PMID 33113804, 2020). "Accumulating in the tumor, CCL21-FA-UCNPs@mesoporous silica induced the migration of CCR7+ DCs and Jurkat T cells." (PMID 33240857, 2020). "In summary, the dual roles of the CCR7/CCL21 axis in protective immunity and tumor promotion suggest that their targeted therapies must be carefully evaluated." (PMID 32340161, 2020). "CCR7 has also been found to induce EMT in PDAC and lung cancer (LC), promote MMP-2 and -9 expression in bladder cancer, and facilitate tumor cell dissemination, migration, and eventually metastasis formation." (PMID 31991604, 2020). "(c) Expression of CCR2, CCR4, CCR5, CCR7, CXCR1, CXCR2 and CXCR7 on tumor-infiltrating mast cells by gating on CD45+CD117+FcεRI+ cells." (PMID 30808413, 2019). "Meanwhile, the expression of chemokine receptors (CCR7 and CXCR4) is reduced, which abrogates the migratory ability of the tumor cells." (PMID 31507423, 2019). "We found that BMDCs cultured with tumor‐conditioned serum had lower MHC‐II, CD86, and CCR7 expression accompanied by higher levels of PD‐L1 compared with the control group." (PMID 30628173, 2019). "AKe was reported to significantly increase E-cadherin expression and reduce CCR7 and CXCR4 level, which are required for tumor migration." (PMID 31507423, 2019). "Matured DCs (≥ 60% upregulation of CD80, CD86, CD83, and CCR7) produced high levels of the Th1 effector cytokine, IL12-p70 (1.2 ng/ml; p < 0.0001), compared to DCs pulsed with tumour lysate, or matured with an interferon-containing cocktail alone." (PMID 30283982, 2019).